CCL3 (C-C motif chemokine ligand 3)
Diseases named in the same sentence as CCL3 in open-access papers (continued):
Sharing a sentence is not in itself a finding about the gene and the disease.
tumor (continued). "Taken together, our findings suggested that the chemokines CCL2, CCL3 and CCL14 not only regulated MO/MΦ chemoattraction, but also controlled mMΦ proliferation within the MM tumor bed and induced MΦ polarization toward mMΦs." (PMID 26155942, 2015). "In whole tumor tissue samples, we found higher TNF-α and CCL2 gene expression, along with higher CCL3 protein expression in cachectic patients, as compared to WSC." (PMID 26732354, 2015). "Our data suggest that a gradient of CCL2 attracts monocytes/macrophages towards the metastatic tumor microenvironment where they are exposed to high levels of CCL2 and are prompted to secrete another chemokine CCL3." (PMID 26275794, 2015). "We found that the sMSCs prepared either in vitro or in vivo specifically produce ANGPT2, CCL2, CCL3, and FSTL1, and most powerfully affect tumor behavior and host immunity by using these molecules (unpublished data except CCL2)." (PMID 25883937, 2015). "CCL3, CCL4, and IL-1β expression was higher in the adipose tissue and tumor tissue in the cachectic group." (PMID 26732354, 2015). "It is reported that the secretory chemokines CCL3 and CCL4 played an important role in the cross talk between CLL cells and their microenvironment, which promoted the proliferation and metastasis of tumor cells." (PMID 24693884, 2014). "Hypomethylated genes in the TNF network were cytokines (CCL3, CCL4, CCL7, CCL8, CCL22, IL21, IL17A, EBI3) that can either stimulate or inhibit tumor growth and progression." (PMID 22768131, 2012). "Previously, it was shown that 4T1 cells produce various chemokines, including CCL2, CCL3, CCL4 and CCL5, that we also detected in the tumor microenvironment, with CCL5 levels being significantly higher in tumors in α-TEA-treated mice." (PMID 21232138, 2011). "Several cytokine mRNAs' (CCL3/MIP-1α, CCL15/MIP-1δ, CXCL1, CXCL5/ENA78, CXCL8/IL8, CXCL9/MIG, CXCL10/IP10) were found to be overexpressed in the tumours while CCL15/MIP-1δ, CXCL5/ENA78 and IL8 mRNAs' were overexpressed in paired normals, as well." (PMID 21092330, 2010). "In this treatment model, the benefit of CCL3 and CCL20-recruited DCs as a tumor treatment was quantified by counting metastatic foci in pulmonary tumor-bearing mice." (PMID 20420712, 2010). "In vivo, vaccination with CCL3 and CCL20-recruited DCs modified with MAGE-1 remarkably inhibited subcutaneous tumor growth and size." (PMID 20420712, 2010). "In this study, CCL3 and CCL20-recruited DCs were modified with a tumor antigen gene and used as vaccines for an anti-tumor immune response ex vivo and in vivo." (PMID 20420712, 2010). "In contrast, EpCAM, IL8, CXCL10/IP10, CCL3/MIP-1α, CCL4/MIP-1β, CCL15/MIP-1δ, PDGFR-B were predominantly elevated in tumours compared to AN and PN." (PMID 21092330, 2010). "In the present study, we demonstrated that F4/80-B220-CD11c+ DC precursors mobilized by CCL3 and CCL20 can induce tumor-specific CTL and elicit potent, therapeutic effects against solid and metastatic tumors when modified with MAGE-1." (PMID 20420712, 2010). "From a functional standpoint, IL-21/IL-15-treated cells secreted copious amounts of IFN-γ, GM-CSF and CCL3/MIP-1α, and expressed cell surface CD107a upon contact with NK-sensitive tumour targets, a measure of exocytosis of NK secretory granules." (PMID 19712464, 2009). "Finally, in the CCL network, CCL3 and CCL3L3 produced by MG1, MG2, tumor-cell clusters 4 and 6, oligodendrocytes, and MDM5 engaged CCR1 on MG3, while CCL5—expressed exclusively by MDM5—also targeted MG3." (PMID 41503214, 2026). "CCR5 facilitates T cell migration to inflammatory or infectious sites by binding to chemokines like CCL3, CCL4, and CCL5, particularly crucial in anti-tumor immunity and chronic inflammation, the infiltration of CCR5+ T cells is associated with the efficacy of immunotherapy." (PMID 41438981, 2025). "Importantly, CCL3 contributed to the observed synergy between PGRN deletion and anti-PD-1 blockade in enhancing anti-tumor responses." (PMID 41153795, 2025).
tumor (continued). "Inhibiting CCL3 activity or its receptor could reduce immunosuppressive effects in the TME, restoring anti-tumor immune responses." (PMID 41376630, 2025). "Additionally, CCL3 enhanced CD8+ T cell proliferation and differentiation by upregulating dendritic cell capacity, which results in T-cell activation in the tumor-draining lymph nodes (TDLN)." (PMID 41153795, 2025). "Likewise, in the flank tumor model, neutralization of IFN-γ and TNF-α resulted in a significant reduction of CCL3 and CCL4 by CD8+ T cells in the tumor bed of LLCova-bearing mice." (PMID 40553564, 2025). "Targeting CCL3 with immunotherapeutic strategies, such as blocking the CCL3/CCR1/CCR5 interaction, could reduce the accumulation of immunosuppressive cells and enhance anti-tumor immune responses." (PMID 41376630, 2025). "Conversely, CCL3 overexpression enhanced TRAF6 and NF-κB levels and drove increased tumor growth." (PMID 41153795, 2025). "Further studies have demonstrated that Cr3+ ions, which are the major degradation product of these nanocomposites, can promote the migration of B7‐H3 CAR‐T cells and the CCL3 and CKCL13 chemokine expression, facilitating the formation of TLS in the tumor tissues." (PMID 38899741, 2025). "Furthermore, certain chemokines secreted by platelets, particularly CCL3, can activate the matrix metalloproteinase-1 (MMP-1) pathway, promoting tumor cell invasion." (PMID 40723913, 2025). "The results revealed that irradiation increased the levels of chemokines involved in the migration of T cells (e.g., CXCL10, CCL2, CCL3, and CCL5) but decreased the levels of proangiogenic factors (e.g., VEGF and basic FGF), which facilitate T cells infiltration into the tumor bed." (PMID 40510363, 2025). "Although the study did not directly address how CCL3 affects immune regulation, the chemokine’s elevation in metastatic cases suggests its involvement in tumor dissemination and microenvironmental remodeling." (PMID 41153795, 2025). "Among them, the chemokine family, including CC (e.g., CCL1, CCL3, CCL5, CCL7, and CCL15), CXC (e.g., CXCL1, CXCL3, CXCL5, and CXCL10), XC (e.g., XCL1 and XCL2), and CX3C (e.g., CX3CL1), plays a pivotal role in tumor development, metastasis, and chemotherapy resistance 30-33." (PMID 40740234, 2025). "The levels of the myeloid cell-secreted cytokines tumor necrosis factor (TNF), C–C motif chemokine ligand 3 and 4 (CCL3 and CCL4), and monocyte chemoattractant protein- 4 (MCP- 4) increased significantly with treatment, while Galectin- 9, involved in tumor immune evasion, decreased." (PMID 40310569, 2025). "Finally, we constructed a 4T1 tumor-bearing mice model to verify the effects of CCL5 and CCL3 in vivo." (PMID 41029711, 2025). "Therefore, the decreased expression of CCL3 in the immune system of CRC patients would lead to impaired immune surveillance and tumor cell killing." (PMID 40484866, 2025). "An agonistic TREM1 monoclonal antibody (PY159) could upregulate the secretion of inflammatory factors such as IFN-γ, CCL3, CCL4, IL-8, and TNF and increased tumor sensitivity to anti-PD-1 therapy in syngeneic mouse tumor models." (PMID 39744496, 2025). "Basophils not only enhance humoral immune function but also liberate intracellular agents causing anti-tumor immunity, including the chemokines CCL3 and CCL4, which expedite CD8+ T-cell infiltration, and the chemokines TNF-α and IL-6, which enhance inflammatory anti-tumor responses." (PMID 39816393, 2024). "However, the top five downregulated genes in state 5 predominantly include members of the C-C motif chemokine ligand family (CCL3, CCL4L2, and CCL4), which augment tumor immunity by attracting lymphocytes and macrophages." (PMID 38993839, 2024). "These three signatures consist of myeloid-focused cytokines (TNFa, GM-CSF, and IL-1b), chemokines (CCL3, CCL4, CCL5, CXCL9, and CXCL10), and an effector T-cell-derived cytokine (IFNg) and represent important aspects of a macrophage-based anti-tumor immune response." (PMID 39199551, 2024).
tumor (continued). "Furthermore, ectopic expression of ID3 in hiPSC-Macs also increased their production of the chemokines CCL3, CCL4 and CCL5, and the cytokines IL-12, IL-15 and IL-18 in response to tumour cells in vitro." (PMID 38326607, 2024). "Consequently, we conclude that PGRN knockout upregulates CCL3 expression, leading to enhanced CD8+ T-cell infiltration and functional activity within TME, ultimately resulting in the inhibition of tumor growth." (PMID 38744851, 2024). "Similarly, immunofluorescence staining in tumoural liver 2 weeks after intraportal injection of KPC cells in wild-type mice indicated that CCL3, CCL4 and CCL5, and IL-12, IL-15 and IL-18 are most prominently produced by KCs present at the tumour margin." (PMID 38326607, 2024). "The anti-CCL3 neutralizing antibody did not affect the tumor growth of the WT group but partially eliminated the inhibitory effect on tumor growth induced by PGRN knockout." (PMID 38744851, 2024). "This was accompanied by KCs expressing CCL3, CCL4, CCL5, IL‐12, IL‐15, and IL‐18, which may contribute to enhanced phagocytosis of tumor cells." (PMID 39220104, 2024). "The expression of CCL3, CCL4, and CCL5 chemokines, also higher, may be major determinants of tumor infiltration by DCs and NKs." (PMID 37675835, 2023). "Inflammatory responses occur at the early stage after LITs, increasing the permeability of tumor vessels and promoting the injured tumor cells to produce chemokines (e.g., CCL2, CCL3, CCL4, CCL8, etc.)and proinflammatory cytokines (e.g., TNF-α, IL-1, IL-6, IL-17, etc.)." (PMID 36831664, 2023). "However, the role of CCL3 and CCL4 appears to exert both antitumor and pro-tumor behavior which is context dependent in solid cancers." (PMID 36639681, 2023). "MDSCs are generated in the bone marrow and their recruitment to the tumor site is dependent on diverse set of chemokines, such as CCL2, CCL3 and CCL4, for the recruitment of M-MDSCs via the C-C chemokine receptor 2 (CCR2) and the ligands of the CXC-chemokine receptor 2 (CXCR2) for PMN-MDSC." (PMID 37370739, 2023). "Using multiplex immunoassays, we examined type I IFN (IFN-α, IFN-β), type II IFN (IFN-γ), proinflammatory cytokine (GM-CSF, IL-6, IL-12p70), and proinflammatory chemokine (CXCL10 [IP-10], CCL2 [MCP-1], CCL3 [MIP-1α], CCL5 [RANTES]) signaling in the tumor microenvironment (TME)." (PMID 36810257, 2023). "While chronic inflammation promotes tumor progression, tumor cells themselves also attract immune cells via chemokines such as IL-8, CCL2 (MCP-1), CCL3 (MIP-1α), CCL5 (RANTES), CXCL6 (huGCP-2), and cytokines such as IL-1β, IL-6, TNFα, GM-CSF, and G-CSF, inducing inflammation." (PMID 36614196, 2023). "As CCR5 binds with high affinity to several ligands that are induced by current BCa therapies (CCL5, CCL3 (MIP-1a), and CCL4 (MIP-1b), CCR5i may augment anti-tumor immune responses." (PMID 37759462, 2023). "CCL2 increased the expression level of the CCR1 ligand CCL3 in MAMs via CCR2, and the signaling generated by the CCL3/CCR1 interaction enhanced and stabilized the cancer cell-MAM interaction in part through integrin α4 binding to VCAM1 expressed on tumor cells in an autocrine manner." (PMID 37208442, 2023). "In addition, a low expression of IL12RB1, CD28, CCL3, and GZMA before treatment in the p16- tumour group conferred a higher rate of failure." (PMID 36835246, 2023). "Chemokines secreted by TAMs, including CCL3, CCL5, CCL15, CCL18, CXCL8 and CXCL12, promote tumor metastasis, angiogenesis, cancer cell survival, immunosuppression and resistance of cancer cells after chemotherapy via CCR1/5, CCR5, CCR1, CCR8, CXCR1/CXCR2, CXCR4, respectively." (PMID 36173487, 2023). "Moreover, we observed upregulated chemokines (such as CCL3/4/5 and CXCL10/11/12) expression in TeMs, suggesting the importance of tumor macrophages in recruiting T cells." (PMID 37488416, 2023).
tumor (continued). "ROS also initiated the inflammatory reaction by the NF-κB pathway to secrete chemokines both in tumor cells and the tumor microenvironment, such as CCL2, CCL3, CXCL2, and CXCl12, which were upregulated by Se-PC PDT, and CCL24 and CXC17, which were downregulated by Se-PC PDT in the tumor niche." (PMID 37994159, 2023). "Notably, NK cells, which displayed high expression levels of GNLY, NKG7, CCL3, and KLRD1, were enriched in tumor tissues, especially in HM tissues." (PMID 37612267, 2023). "Among them, the top up-regulated genes in tumor cells were those related to cancer progression (eg, AREG, CCL3, PLEKHA5, VCAM1 and MCM7), which might be the targets of innovative treatments." (PMID 36417130, 2023). "We found that cisplatin-pretreated tumor cells stimulate neutrophils which expressed higher levels of cytotoxic effectors, including TNF-α, GZMB, and ELANE, and pro-inflammatory cytokines, such as CCL2, CCL3, CXCL10, CXCL11, and IL12." (PMID 35784745, 2022). "Besides, MDSCs can produce high levels of some chemokines, such as CCL3, CCL4, and CCL5, which drive CCR5-expressing Treg cells through the tumor microenvironment, supporting the tumor growth." (PMID 35757002, 2022). "As revealed by our gene set enrichment analysis, many factors being elevated in the serum of LHMS patients, e.g., the chemokines CCL3, CCL20, MCP-3, and MCP-4, are involved in chemotaxis, migration, and recruitment of monocytic and lymphocytic immune cells into the tumor." (PMID 36230528, 2022). "Intratumoural injection of adenovirus vector armed with CCL3, followed by the adoptive transfer of activated T cells, delayed tumour growth significantly, although survival was not heightened compared to adoptive transfer with a control virus in a mouse model." (PMID 35205725, 2022). "Interestingly, CCR5 ligands: CCL3, CCL4 and CCL5 were detected in the majority of supernatants harvested from dissociated tumour biopsy and CUSA, but little was detected in GNS cell supernatants." (PMID 35464424, 2022). "However, Mono-FCGR3A in high tumor infiltration group expressed lower levels of MHC molecules, inflammatory cytokines and chemokines (HLA-DRB1/HLA-DPB1, TNF, IL1B, CCL3 and CCL4), which meant the sub-cluster was less involved in immune responses." (PMID 36532059, 2022). "Overall, the described involvement of the CCR5 ligands CCL5 and CCL3 in CRC-driven immune escape mechanisms and their tumor-promoting properties seemed to outweigh the capacity of CCL4 to trigger the recruitment of peripheral effector T cells in CRC metastases via CCR5 engagement." (PMID 36428508, 2022). "Despite implantation of identical 6DT1 cells, CLIC4 deficiency in the host microenvironment led to relative increases in many factors within the primary tumor proteome, including pro-inflammatory cytokines such as CCL3, also known as macrophage inflammatory protein 1-alpha, at both 14 and 28 days." (PMID 35727842, 2022). "Comparing immune cells and immune-related gene expression across different FAT statuses, we found that in FAT mutant STAD, chemokines, such as CCL3, CCL4, CXCL1, CXCL3, CXCL9, and CXCL10, recruited and activated cytotoxic T lymphocytes in the tumor tissue to perform an antitumor effect." (PMID 35836939, 2022). "CCL3 and CCL4 are well-known chemotactic factors influencing tumor macrophage populations." (PMID 35939336, 2022). "CCL3, CCL19, CCL21, and XCL1 exhibited potent anti-tumor activities in vivo, although they might differentially regulate immune cells in the TME and antigen transfer to lymph nodes." (PMID 36654820, 2022). "The MIP-1α/CCL3 and MIP-1β/CCL4 chemokines may display either anti-tumor or tumor-promoting activity, and the available data seem to support both roles in equal measures." (PMID 34885960, 2021). "The expression of CCL4 and CXCL2 from MIP chemokines was significantly, and CCL3 insignificantly, upregulated in tumors compared to tumor-adjacent non-transformed tissue by 1.4-fold, 2.0-fold, and 1.3-fold, respectively." (PMID 34885960, 2021).
tumor (continued). "The non-paired analysis confirmed significantly higher CCL19 and significantly lower CCL4 and CXCL2 expression in tumor-adjacent tissue than in tumors, and a lack of difference in the case of CCL3." (PMID 34885960, 2021). "The anti-tumor “N1” phenotype exhibited increased tumor cytotoxicity, elevated expression of CXCL13, CCL3, CCL6, CXCL10, TNFα and ICAM-1 and low ARG1 content, while the pro-tumor “N2” neutrophils expressed high levels of ARG1, MMP9, VEGF and several cytokines, including CCL2, CCL5, CCL17 and CXCL4." (PMID 34572138, 2021). "Moreover, pro-inflammatory cytokines (IFN-γ, TNF-α) and chemokines (CCL3, CCL4, and CCL5) secreted by NK cells stimulate other lymphocyte populations in the tumor microenvironment or exert a direct anti-tumor effect." (PMID 34203935, 2021). "Tumor CCL2 and CCL7 increased along with advancing T and CCL3, and CCL4 along with the N stage." (PMID 34885960, 2021). "The accumulated evidences indicated that M1 conditioned medium (M1 CM) could inhibit tumor growth via TNF-α, CXCL9, IFN-γ, or CCL3 in different types of cancers." (PMID 33175182, 2021). "Chemokines, such as CCL3, CCL4, and CCL5 can promote the recruitment of T cells to the tumor site." (PMID 33922465, 2021). "Collectively, our results indicate that rBFT1 serves as a tumor promoter and plays a crucial role in inducing the proliferation of CRC via accelerating CCL3-related molecular pathway, thus giving insights into mechanistic underpinnings for the prevention and treatment of CRC." (PMID 33981848, 2021). "Factors that can promote the anti-tumor neutrophil phenotype include chemokines (e.g., CXCL2, CXCL5, CXCL8, CCL2, CCL3, CCL5, CXCL12 (SDF-1), CXCL16 and IL-8) alone or together with G-CSF/GM-CSF, TNFα, IFNβ, IFNγ, IFNγ together with TNFα, Resolvin D1, hepatocyte growth factor (HGF) and IL-17." (PMID 34572138, 2021). "CCL2, CCL3, TIMP-1, and IL-13 are products readily found in an immune response that is driven by M2 macrophages, which correspond to a tumour growth-promoting phenotype that aids tumour cell proliferation, reduction of an antigen-specific immune responses, and increased angiogenesis." (PMID 33494138, 2021). "Indeed, these studies suggest that the major monocyte recruiting pathways (M-CSF/CSF-1R, CCL2/CCR2, CCL3/CCR1, CCL3/CCR5, CCL5/CCR5 and CX3CL1/CX3CR1) enable tumor survival by supplying the TME with pro-tumorigenic TAMs." (PMID 34988021, 2021). "CEA-TCB-treated tumors displayed a clear upregulation of several pro-inflammatory cytokines and chemokines [MIPα (CCL3), CXCL10, CXCL13, CXCL9, IL-16, and I-TAC (CXCL11)], an increase in intra-tumor CD3+, CD4+, CD8+ T-cells that express high levels of 4-1BB, PD-1, and upregulation of GZMB." (PMID 33330050, 2020). "CCL3 expression in nonneoplastic stromal and/or inflammatory cells in the tumor microenvironment was also described in some of those studies." (PMID 32457351, 2020). "Both CCL3 and CCR5 immunoreactivities were detected diffusely in the tumor nests." (PMID 32457351, 2020). "Furthermore, we show that local chemokine delivery triggers directed CTL movement through dense tumour tissue in vivo, and sustained secretion of CCL3 and CCL4 from tumours promotes CTL recruitment." (PMID 33046212, 2020). "Although blood and tumor-infiltrating NK cells express predominantly perforin and granzyme genes that are related to cytotoxicity, tumor-infiltrating NK cells upregulate XCL1, XCL2, CCL3, CCL4, CCL4L2, and CCL5 that are chemokine genes." (PMID 33424862, 2020). "Cytokines released from tumor-residing cells including tumor cell–derived IL-4, IL-10, CCL2, CCL3, CCL4, and CSF1; Treg-derived IL-10; B cell–produced immunoglobulins; Th2-derived IL-4 and IL-13; and MSC-derived MFG-E8 promote the polarization into a protumor phenotype." (PMID 31256327, 2020). "Thus, the CCL3/CCL5–CCR5 and CCL5–CCR3 axes appear to play a role in CD4+ T cell infiltration in the tumour." (PMID 32439888, 2020).